EGFR (epidermal growth factor receptor)
Diseases named in the same sentence as EGFR in open-access papers (continued):
Sharing a sentence is not in itself a finding about the gene and the disease.
tumor (continued). "Additionally, in the MeIQx-, urethane- and X-ray-treated models, G/C→C/G (AH), A/T→T/A (Ad), and A/T→T/A (Ad) transversions in Kras, respectively, were detected in a neoplasm, while EGFR mutations with amino acid substitution were detected in X-ray-induced tumors (4/12; 33%)." (PMID 34200786, 2021). "Furthermore, 6 EGFR mutation‐dependent and 2 EGFR wild type‐specific tumor‐derived exosomal miRNAs that were expressed at higher levels, and 7 EGFR mutation‐dependent and 2 EGFR wild type‐specific miRNAs that were expressed at significantly lower levels were validated." (PMID 33682961, 2021). "To assess whether exogenous IgG4 antibodies could similarly modify the effector response of macrophages, we used two isotype variants of the anti-EGFR therapeutic anti-tumor antibody cetuximab, both with the same variable regions, but with γ1 or γ4 constant domains." (PMID 33628623, 2021). "Thus, when blocked, EGFR would reduce damage caused by tumor cells." (PMID 34452282, 2021). "Another factor that motivates the exploration of EGFR as a possible target in cancer and angiogenesis is associated with the fact that, while this receptor is predominantly not present in standard endothelial cells, selective overexpression commonly occurs by the tumor-related vasculature." (PMID 33855679, 2021). "However, it remains unclear whether EGFR-mutated NSCLCs with a high programmed death-ligand-1 (PD-L1) expression (tumor proportion score ≥ 50%) respond to PD-1 inhibitors." (PMID 32705363, 2021). "However, specific EGFR mutations, also known as activating or sensitizing mutations, can cause constitutive activation of the receptor, leading to uncontrolled cell division and tumor pathogenesis." (PMID 34834454, 2021). "This implied that EGFR addiction for tumor growth might underlie the clinical value of TKIs." (PMID 34367939, 2021). "In addition QC6352 can also inhibit the expression of epidermal growth factor receptor (EGFR), which may explain the decrease in tumor-initiating cell populations associated with chemotherapy resistance." (PMID 35186950, 2021). "Furthermore, osimertinib with necitumumab (another anti-EGFR mAb) combination therapy achieved a median PFS of 6.4 months in a tumour containing the EGFR C797S variant, which is predicted to have increased intermolecular interaction due to hydrogen bonding between the mutation and EGFR R841." (PMID 34069119, 2021). "Thus, we conduct this study to determine whether tumor PD-L1 expression associates with efficacy of EGFR-TKI treatment." (PMID 34449486, 2021). "Furthermore, EC- and PC-derived HB-EGF (heparin-binding epidermal growth factor-like growth factor) activates EGFR (epidermal growth factor receptor) specifically in tumor-associated perivascular cells, resulting in increased PC coverage and enhanced angiogenesis." (PMID 34179005, 2021). "Furthermore, greater growth inhibition of EGFR-positive BRAF mutated tumours was measured following a single dose of Albu-LiTE-HB construct compared to the Fc-less LiTE format and a full-length anti-EGFR monoclonal antibody in a new AlbuMus RAG1 knockout model introduced in this work." (PMID 33686177, 2021). "Also, this is particularly significant because HHLA2 expression may assist identification of a group of patients who might do poorly in spite of tyrosine kinase inhibitors (TKIs) for EGFR-mutated tumours." (PMID 34181347, 2021). "Notably, the EGFR/AKT signaling pathway is strongly associated with tumor angiogenesis." (PMID 34294040, 2021). "Primary tumor location (i.e., left or right colon) has been linked to differences in clinical and biological characteristics between patients and, like mutational status, may be predictive of anti-EGFR treatment response." (PMID 34298750, 2021). "However, this apparent contradiction may be explained by the increased tumor burden in mice deficient in EGFR signaling." (PMID 33976143, 2021).
tumor (continued). "False-negative results of RAS testing, which may be attributed to the failure of tumor cell dissection or poor performance of DNA assays, possess significant risks for the patient, as EGFR inhibition in RAS-mutated tumors may facilitate the disease’s progression." (PMID 34681592, 2021). "Scientific studies have shown that aspects of the tumor microenvironment, such as survival signals from fibroblasts around cancer cells and poor vascularization around cancer cells, may cause cancer cells to survive EGFR-TKI monotherapy." (PMID 34831415, 2021). "In NSCLC, ctDNA could be used to track and examine the effect of “druggable” mutations, e.g., of EGFR, and together with CTCs to identify expression of potentially crucial players and of changes in tumor characteristics before, during, and after appropriate treatments." (PMID 33947159, 2021). "Importantly, analysis using immunohistochemistry and gene amplification by fluorescence in situ hybridization (FISH) showed that progression from benign to atypical or anaplastic MGMs associates with an increase in EGFR protein content, so that EGFR immunostaining directly correlates to tumor grade." (PMID 34768783, 2021). "For instance, EGFR inhibitors, such as gefitinib, erlotinib, or afatinib, can effectively shrink tumors for several months; these drugs eventually stop working for most patients, usually because the cancer cells within the tumor develop additional mutation(s) in the EGFR gene." (PMID 33845897, 2021). "Both increased EGFR activation and overexpression, most often resulting from somatic mutations, gene amplification, transcriptional upregulation, or ligand overproduction, promote cancer development and progression, including tumor angiogenesis, metastasis, and resistance to apoptosis." (PMID 34070597, 2021). "EGFR tyrosine kinase inhibitors (TKIs, gefitinib, erlotinib, afatinib) are employed for those tumors in which this receptor is overexpressed or constitutively activated by mutations; however, cancer cells are able to escape such inhibition leading to tumor relapse." (PMID 33498502, 2021). "In addition, Eph has been reported to suppress the wild type of EGFR pathway, whereas in patients with EGFR-mutation, the EGFR-independent tumor growth-promoting effects may outweigh the inhibitory effects of EphB4." (PMID 34445227, 2021). "Spliceosomal dysregulation may switch FGFR2b to FGFR2c, altering ligand binding and driving dedifferentiation or EMT, e.g., during progression of hormone-dependent to -resistant cancers, or associated with constitutive EGFR activation in HPV16 E5-induced neoplasia." (PMID 34007277, 2021). "Moreover, analysis on liquid biopsy becomes the best feasible diagnostic tool when EGFR detection in tumor tissue takes more than 2 weeks, or tissue biopsy may be risky or contraindicated." (PMID 34680416, 2021). "Fourth, EGFR mutations could be the link between tumor location and prognosis." (PMID 32913267, 2020). "Therefore, we hypothesized that NT5DC2 promotes tumor growth by physically associating with EGFR and facilitating EGFR expression." (PMID 32382041, 2020). "While tumour tissue is the commonly preferred standard sample for the evaluation of EGFR mutations, for many patients such samples are not available, which is the reason why a study has been undertaken to search for a surrogate marker for EGFR status through a more accessible way." (PMID 33198090, 2020). "In addition, osimertinib-induced tumor shrinkage more markedly in patients with pIGF-1R-high expression when compared with pIGF-1R-low expression (p = 0.011), consistent with the results of the experiments performed using EGFR-mutated NSCLC cell lines." (PMID 32929081, 2020). "However, the efficacy of immunotherapy depends not only on immune infiltration and PD-L1 expression, but also on the tumor mutation burden, epidermal growth factor receptor mutation status and other unknown factors." (PMID 33091876, 2020).
tumor (continued). "Therefore, the apparent association between tumor epithelial phenotype and sensitivity to EGFR TKIs might have been driven by the presence of activating EGFR mutations in tumors with more epithelial phenotype." (PMID 32292420, 2020). "Therefore, the biopsy specimen may be inadequate, and it may be impossible to thoroughly study the EGFR mutation characteristics of the entire tumor." (PMID 33370365, 2020). "In the early-stage NSCLC, Sel-Cap liquid biopsy was able to detect more than half the EGFR mutations, which were detected in tumor tissue (sensitivity: 50% and 78% for Ex19del and L858R respectively, with tumor results as the references), while the conventional NGS could not detect any." (PMID 33266057, 2020). "Thus, mutations or amplification of EGFR result in tumor growth/cancer." (PMID 32560187, 2020). "Furthermore, TCR sequencing might be applicable for the treatment selection in patients with EGFR mutations by evaluating the proportions of TCRβ clones in the tumor." (PMID 32365882, 2020). "By elucidating the adaptation mechanism following the initial treatment with EGFR-TKIs, we could develop novel initiation therapies to eradicate tumor cells, and thereby further improve the outcome of advanced EGFR-mutated NSCLC by preventing the development of acquired resistance." (PMID 32929081, 2020). "However, novel compounds targeting tumor‐specific molecular changes, such as EGFR and BRAF mutations, and ALK fusions, or immunomodulatory agents activating anti‐tumor immune responses, are challenging this paradigm, and some of these drugs show intracerebral efficacy." (PMID 32858763, 2020). "The false-negative results may be due to the sensitivity of the technique for EGFR detection, in particular in the case of a very low allele frequency, but also in the case of a low percentage of tumor cells with the EGFR mutation in the tissue section before DNA extraction." (PMID 32294880, 2020). "Furthermore, this tumor microenvironment cross-talk may provide an explanation for the inefficiency in detecting EGFR mutations in cfDNA samples in this T1 stage cohort." (PMID 33247113, 2020). "However, tumor cells may develop mutations to the EGFR extracellular binding domain and gain resistance against those antibodies." (PMID 33333826, 2020). "For instance, in 50%–60% of cases, treating an EGFR-mutant primary tumor with targeted therapies induces a positive selection of resistant cancer cells within the tumor due to the acquisition of a secondary mutation, T790M in the EGFR protein that occurs outside of the ATP binding site." (PMID 32111002, 2020). "Indeed, using an experimental design based on two independent cohorts, we showed that the dPCR assay was better than standard methods and was able to detect the main somatic EGFR alterations in DNA extracted from FFPE tumor samples with a diagnostic performance of 100%." (PMID 32303258, 2020). "However, there is some evidence to suggest that low expression of TYMS and EGFR is associated with increased tumor regression rates and low p21 expression may be associated with improved survival in rectal cancer." (PMID 32231042, 2020). "In addition, xenograft tumor models with the nude mouse using DLD1 cells with WT or mutated KRAS were established to examine the effects of AMPK activation on KRAS mutation-mediated anti-EGFR antibody resistance." (PMID 32703218, 2020). "Since osimertinib is a selective inhibitor of mutated EGFR in tumor cells and spares wild type EGFR expressed mainly in host cells, the feasibility of a transient combination of IGF-1R inhibitor with osimertinib may be more superior to first or second generation EGFR-TKIs." (PMID 32929081, 2020). "In this paper, we have presented a novel mathematical model of the co-evolution of three distinct tumour cell sub-populations to investigate the nature of interactions between cells with two common mutations occurring in GBMs, namely amplification of the genes encoding the EGFR and PDGFRA proteins." (PMID 33120534, 2020).
tumor (continued). "In this example, the increase of the EGFR T790M mutation in EV-DNA from the BW-derived sample could be detected even though the primary tumor size in the CT image was decreased, which was much earlier than the CT image could identify the metastasis to the brain." (PMID 33007940, 2020). "However, repeated tissue biopsies in patients with advanced disease is not always feasible, due to the invasiveness of the intervention, and when it is possible it may be difficult to obtain enough tumor DNA for the EGFR mutation test." (PMID 33297595, 2020). "Indeed, the reported PIK3CA co-mutated cases with allegedly acquired or intrinsic resistance to EGFR-TKIs often harbored mutations in other oncogenes or in tumor-suppressor genes that could be the actual cause of TKI-resistance." (PMID 31266248, 2019). "However, tumor biopsies for the detection of EGFR mutations have limitations." (PMID 31380265, 2019). "PTEN (phosphatase and tensin homologue), a tumor suppressor, regulating cell division and apoptosis, has been explored, and significant evidence suggests a role in cetuximab and panitumumab resistance linked to the epidermal growth factor receptor (EGFR) signal transduction pathway." (PMID 31717544, 2019). "As such, differences in EGFR mutation status may lead to differences in tumor glucose metabolism." (PMID 31380265, 2019). "To validate whether EGFR protein expression and specifically its expression pattern as mcEGFR or nEGFR may provide paired associations with pathological characteristics, we conducted immunohistochemistry on a total number of 502 cases covering 27 tumor types." (PMID 30956774, 2019). "Second, further EGFR mutation surveys of surgical brain tissue should be conducted to clarify the exact molecular changes in metastatic lesions, given that genetic heterogeneity between the primary tumor and CNS metastases may exist." (PMID 31048854, 2019). "High EMT (HR = 2.19, p = 0.0014), EGFR (HR = 1.82, p = 0.0038), acute hypoxia (HR = 1.64, p = 0.017), DNA CL repair defect (HR = 1.8, p = 0.0085) and chronic hypoxia scores (HR = 1.7, p = 0.015) and tumor volumes (HR = 1.72, p = 0.036) are associated with a worse progression free survival (PFS)." (PMID 31998639, 2019). "However, they utilized either small interfering RNA (siRNA) or short hairpin RNA (shRNA) approach or focused on small subsets of genes (such as tumor suppressors, oncogenes and genes encoding kinases), and identified distinct genetic modifiers of EGFR TKI sensitivity." (PMID 31741433, 2019). "Finally, we analysed the possible role of immunotherapy in EGFR mutated tumours." (PMID 31554160, 2019). "Moreover, analyzing mRNA and protein levels of PD-L1 in the Cancer Genome Atlas (TCGA) and internal database (Guangdong Lung Cancer Institute; GLCI), lower PD-L1 mRNA and PD-L1 protein expression were detected in the EGFR mutated NSCLC samples compared with the wild-type tumor samples." (PMID 31554160, 2019). "Similarly, ctDNA in plasma provides an alternative to tumor samples for EGFR mutation analysis, and plasma gene mutations showed greater advantages than solid tumor cells for revealing the genetic landscape of primary and metastatic lesions, which are relatively limited." (PMID 31368671, 2019). "Consequently, targeting a single activating EGFR-mutation will eventually result in treatment failure, because pre-existing or swiftly induced resistant cells will, by variable mechanisms and at different times and tumor locations, expand and prevail." (PMID 31266248, 2019). "Recently, study implies sortilin is a key regulator of epidermal growth factor receptor (EGFR) internalization and limits the EGFR signaling and loss of sortilin in tumor cells promoted cell proliferation by sustaining EGFR signaling at the cell surface, ultimately accelerating tumor growth." (PMID 30814514, 2019).
tumor (continued). "Moreover, at CNA level, we found high ITH of druggable gene EGFR and FGFR1 in approximately 50% FGFR1- and EGFR-amplified cases, indicating that the mutation status of these two targets from single-tumor sequencing may underestimate their ITH." (PMID 30975989, 2019). "However, the underlying mechanism by which statins exert its anti-tumor effects in EGFR-TKI resistant NSCLC remains unclear, and it is the focus of the present study." (PMID 31534543, 2019). "The routine EGFR mutations detection methods inherently lose all spatial information during pre-treatment process, may obscure the difference between separate spatial regions of tumor tissues." (PMID 31555581, 2019). "In the absence of the normal cells in these areas, the mutation signal would be equivalent to that of the wild-type; however, a tumor is always mixed with normal cells, which might result in a diluted EGFR mutation signal that is below the detection threshold of the method." (PMID 31014278, 2019). "The availability of these tumor samples with annotated clinical data offers the possibility to identify novel genetic alterations that might be associated with de novo resistance to anti-EGFR MoAbs." (PMID 31226844, 2019). "Collectively, the data infer that, as for any TKI-resistant mutation, a certain number (clone) of T790M-positive cells may co-exist with sensitizing EGFR-mutations in the heterogenous tumor tissue before treatment with 1G/2G TKIs and hamper the efficacy of these drugs." (PMID 31266248, 2019). "In addition, single tumor cell analysis might provide a deeper insight into the occurrence of intratumoral heterogeneity of EGFR-activating mutations." (PMID 31014278, 2019). "Indeed, anti-EGFR antibodies plus CAT tend to cause early tumor shrinkage which improves prognosis." (PMID 31103951, 2019). "Therefore, when the status of EGFR mutations cannot be tested in a timely manner because of inadequate tumor tissue or when treatment for NSCLC is urgent for clinical reasons, the IHC staining result of TTF-1 may be used to guide systemic anticancer therapy." (PMID 30736438, 2019). "Therefore, despite how EGFR mutations upregulate the constitutive expression of PD-L1 in tumor cells, the concomitant shortage of activated tumor infiltrating lymphocytes in EGFR-mutated NSCLC may weaken the inducible PD-L1 expression." (PMID 31258527, 2019). "The main reason for this may be that the key mechanism of the EGFR antibody is achieved by blocking the EGFR signaling pathway when accumulating around the tumor, whereas gene mutations and amplifications of the EGFR downstream signaling pathways are frequently noted in ESCC." (PMID 30372581, 2019). "Because it wouldn’t have to be administered to patients, we believe that this fluorescent tracer could be used as a pre-test diagnostic tool to confirm that the sampling of the tumour was adequate in patient with progressive disease under EGFR specific TKI therapy." (PMID 30612556, 2019). "Therefore, we hypothesize that minor tumor clones carrying KRAS variants might be enriched during tumor progression in the metastatic sites, thus determining resistance to anti-EGFR MoAbs and positivity of liquid biopsy." (PMID 31226844, 2019). "Aiming to fill up the gap, we demonstrated that high tumor mutation load might mediate tumor progression and recurrence by activating the immune escape mechanism and that high mutation load in the EGFR wild‐type patients correlated with worse relapse‐free survival." (PMID 30941903, 2019). "Tumor-associated fibroblasts induce also the direct proliferation of keratinocytes, releasing a ligand of epidermal growth factor receptor (EGFR), namely heparin-binding EGF like growth factor (HBEGF), against which further studies may create monoclonal antibodies." (PMID 31096567, 2019).